INS (insulin)
Diseases named in the same sentence as INS in open-access papers (continued):
Sharing a sentence is not in itself a finding about the gene and the disease.
type 2 diabetes (continued). "Moreover, IR and insufficient insulin secretion are the main factors associated with the development of type 2 diabetes mellitus (T2DM) and are regarded as the important clinical markers for the early diagnosis and late follow-up of such condition." (PMID 31686981, 2019). "Defects in this pathway result in impaired insulin secretion and are a hallmark of type 2 diabetes." (PMID 31533953, 2019). "Our aim was to investigate whether human insulin (HI) or insulin glargine treatment could promote the proliferation of thyroid cells and determine the association between type 2 diabetes and thyroid disease." (PMID 31555212, 2019). "Despite the vast mechanistic evidence linking inflammation and insulin resistance, the root cause behind the low-grade inflammatory state seen in obesity and type 2 diabetes remains unclear, particularly in humans." (PMID 29649324, 2018). "The double-blind Trial Comparing Cardiovascular Safety of Insulin Degludec vs Insulin Glargine in Patients with Type 2 Diabetes at High Risk of Cardiovascular Events (DEVOTE) was initiated to assess the cardiovascular safety of insulin degludec compared with insulin glargine U100." (PMID 28913543, 2018). "Additionally, drugs designed to stimulate insulin have been associated with major adverse events in people with type 2 diabetes." (PMID 30126094, 2018). "Second, reduced FFA oxidation, which was observed under severe hypoxia, represents a feature typically observed in obese and type 2 diabetes subjects causally associated with increased intracellular lipid content, impaired insulin signaling, and reduced glucose uptake." (PMID 30386299, 2018). "Higher severity of depressive symptoms was associated with the use of insulin and with coma (PHQ-9 mean = 8.32), limb amputation (PHQ-9 mean = 7.55), circulatory problems (PHQ-9 mean = 6.94), infarction (PHQ-9 mean = 6.83), diabetic foot (PHQ-9 mean = 6.62), and kidney problems (PHQ-9 mean = 6.68)." (PMID 30652778, 2018). "Prevalence of type 2 diabetes is the cause of great social cost, since its treatment involves the use of insulin supplement and oral antidiabetic drugs and the management of complications that may arise." (PMID 30013597, 2018). "Impaired insulin sensitivity is a key abnormality underlying the development of type 2 diabetes." (PMID 29940866, 2018). "The finding of lower concentration of insulin in the exercise group is clinically important as this may reduce the risk of future type 2 diabetes." (PMID 29310617, 2018). "Identifying the molecular mechanisms underlying improved insulin sensitivity following exercise training could provide novel therapeutic targets to treat insulin-resistant and type-2 diabetics." (PMID 30013070, 2018). "VATs Tregs are necessary for restore the insulin sensitivity in type-2 diabetes, so decreased VATs Tregs in HT model might associate with the decrease of insulin sensitivity in HT model mice." (PMID 29541033, 2018). "Type 2 diabetes is often linked with impaired proximal insulin signaling." (PMID 30521580, 2018). "A hallmark of type 2 diabetes is a reduced insulin secretory capacity." (PMID 30166558, 2018). "However, intake of lean-fish, which contain relatively low amounts of omega-3 fatty acids, has also been associated with beneficial effects on lipid metabolism, and on insulin sensitivity and the risk of type 2 diabetes." (PMID 29751643, 2018). "The higher intra-individual variability of fasting insulin, but also of HbA1c, compared with glucose may partly explain the weaker associations with type 2 diabetes." (PMID 29018885, 2018). "The second set of genes LIM homeobox transcription factor 1 alpha (LMX1A), solute carrier family 30 member 8 (SLC30A8) is associated with insulin metabolism and resistance, a feature of some patients in whom type 2 diabetes is an accompanying comorbidity of vestibular neuritis." (PMID 30079052, 2018).
type 2 diabetes (continued). "On the other hand, several manipulations can lead to diabetes type 2: mutations in the insulin pathway components downstream from the ILPs, dietary manipulations leading to obesity, metabolic imbalance, and hyperglycemia, or studies in other Drosophila species with different lifestyles/diets." (PMID 29854726, 2018). "Previous studies have identified some genetic variants associated with insulin signaling and type II diabetes, suggesting that further studies may help to uncover the relationship between insulin signaling and AD pathogenesis." (PMID 30486438, 2018). "The liver is an insulin sensitive organ that plays a key role in the regulation of whole body energy homeostasis, and hepatic IR immensely increases the risk of impaired fasting glucose and type 2 diabetes." (PMID 29393871, 2018). "Moreover, the pathways enriched fast evolving genes include insulin signaling pathway, mTOR signaling pathway, and type II diabetes-associated pathways, all of which are important for the regulation of blood glucose." (PMID 28900766, 2018). "However, we consider this and try to consider the two most important pathogenetic mechanisms linked to human type 2 diabetes, i.e., insulin secretion and insulin resistance." (PMID 29682407, 2018). "High postprandial glucose and insulin concentrations in the blood may induce oxidative stress and low-grade inflammation, and result in decreased insulin sensitivity and subsequent increased risk of developing type-2 diabetes." (PMID 28417207, 2018). "The aim of this study was to determine whether random non-fasting C-peptide (rCP) measurement can be used to assess hypoglycaemia risk in insulin-treated type 2 diabetes." (PMID 28983693, 2018). "Interestingly, epidemiologic studies have demonstrated that the prevalence of type-2 diabetes, a metabolic disease mainly caused by defective insulin signaling, is higher in patients with HD than in healthy controls." (PMID 30149534, 2018). "Failure of response to insulin is the primary cause of type 2 diabetes." (PMID 30513975, 2018). "However, while insulin is traditionally considered to be the most effective glucose-lowering therapy, and often becomes necessary as type 2 diabetes progresses, it is associated with an increased risk of hypoglycaemia." (PMID 28913575, 2018). "To identify genetic contributions to type 2 diabetes (T2D) and related glycemic traits (fasting glucose, fasting insulin, and HbA1c), we conducted genome-wide association analyses (GWAS) in up to 7,178 Chinese subjects from nine provinces in the China Health and Nutrition Survey (CHNS)." (PMID 29621232, 2018). "However, Asians are more susceptible to type 2 diabetes under the insulin resistant condition since their insulin secretory capacity and β-cell mass are low." (PMID 30041479, 2018). "CCN5/WISP2 was also positively correlated with markers of ectopic fat accumulation (i.e.,fat in liver or non-subcutaneous / intra-abdominal adipose tissue) and negatively correlated with whole-body insulin sensitivity, a marker of risk of developing type 2 diabetes." (PMID 29247377, 2018). "The relation of obesity, type 2 diabetes, and a sedentary lifestyle, with risk of several solid tumors, has led to the hypothesis that high insulin levels may increase risk of cancer." (PMID 29713614, 2018). "Nevertheless, Eaton and Eaton observed that the percentage of lean body mass is critical in avoiding the hyperinsulinaemia which predisposes individuals to type II diabetes because a greater insulin secretion is required for any given glucose load where levels of body fat are disproportionate." (PMID 29755739, 2018). "However, higher concentrations of brunch-chain amino acids in blood are associated with risks of developing type 2 diabetes, leucine, alanine, glutamine, glutamate, and arginine stimulate β-cell activity and insulin secretion." (PMID 30513975, 2018).
type 2 diabetes (continued). "In type 2 diabetes, amyloid oligomers, chronic hyperglycemia, lipotoxicity, and pro-inflammatory cytokines are detrimental to beta-cells, causing apoptosis and impaired insulin secretion." (PMID 29789539, 2018). "Loss of first-phase insulin release is an early pathogenic feature of type 2 diabetes (T2D)." (PMID 29854823, 2018). "Interestingly, hypoglycaemia risk in type 1 and type 2 diabetes was comparable in one study in which participants were matched for duration of treatment with insulin." (PMID 28660491, 2018). "Also in Drosophila malfunctioning of insulin signaling, induced either by mutations or by feeding flies with a sugar rich diet, produce diabetic hallmarks that mimic type 2 diabetes (reviewed in34)." (PMID 30061626, 2018). "Since increased systemic iron is associated with the risk of type-2-diabetes, further studies were directed at whether PrP-mediated change in pancreatic β-cell iron influences insulin production and/or secretion and blood glucose levels." (PMID 29700330, 2018). "Interestingly, high fructose diet-induced type 2 diabetes in rats was found to associate with a decline in serum H2S level and supplementation with H2S improved insulin sensitivity, reduced triglyceride levels, and enhanced oxidative stress tolerance." (PMID 30510624, 2018). "We found significantly less treatment discontinuation and lower risk of hypoglycemia in patients with type 2 diabetes newly dispensed with DPP-4 inhibitors compared to those initiating NPH insulin, when these agents were used as third-line therapy after metformin and sulfonylurea." (PMID 29713649, 2018). "For people with type 2 diabetes, the use of an insulin-stimulating drug has been associated with adverse cardiovascular outcomes and there is evidence to suggest that protein restriction may slow the progression of diabetic kidney disease." (PMID 30126094, 2018). "Generally these were cross-sectional analyses assessing total circulating osteocalcin which have associated lower osteocalcin concentrations with higher risk of Type 2 diabetes, higher body mass index (BMI) and plasma glucose concentrations, lower insulin sensitivity." (PMID 29966260, 2018). "We therefore aimed to determine whether rCP measurement can be used to assess risk of hypoglycaemia in insulin-treated patients with a clinical diagnosis of type 2 diabetes." (PMID 28983693, 2018). "Dietary factors may increase the risk of type 2 diabetes directly through their impact on glucose-insulin responses and indirectly by promoting excessive weight gain." (PMID 30383280, 2018). "Indeed, it has been demonstrated that breastfeeding is associated with a reduced risk of type 2 diabetes, with lower blood glucose and serum insulin concentrations during infancy and with lower insulin levels in adulthood." (PMID 29472867, 2018). "Reducing postprandial insulin with higher fiber intakes has beneficial metabolic effects in healthy overweight individuals who are at risk of developing hyperinsulinemia, an early abnormality preceding the development of type 2 diabetes." (PMID 28368334, 2017). "Meanwhile, reduced insulin sensitivity is the pathophysiologic basis of type 2 diabetes and may underlie above cited risks factors." (PMID 28912840, 2017). "Also, SSRI decreased insulin secretion in older adults and increased the risk of insulin dependence in patents with type 2 diabetes." (PMID 29064009, 2017). "Therefore, development of new type of insulin sensitizers for treating type 2 diabetes and associated complications remains of great interest and potential." (PMID 29056962, 2017). "MRI studies show that gray matter loss, insulin resistance, and medial temporal lobe atrophy are associated with AD, traits also present in patients with type 2 diabetes." (PMID 28424581, 2017).
type 2 diabetes (continued). "Emerging studies suggest a role of VD deficiency in the etiology of type 2 diabetes, although it has been argued that the influence of VD could be weak and that obesity may modify the association between 25-OH-VD and insulin sensitivity." (PMID 29112142, 2017). "Although acute caffeine administration leads to reduced insulin sensitivity, caffeine may contribute to the effects of regular coffee use associated with decreasing the incidence of type 2 diabetes." (PMID 29084147, 2017). "Second, we found that wearable sensors can reveal physiological differences between insulin-sensitive and insulin-resistant individuals, raising the possibility that these sensors could help detect risk for type 2 diabetes." (PMID 28081144, 2017). "Several potential mechanisms may contribute to a lower risk of type 2 diabetes and cardiovascular disease associated with smoking cessation, including improved insulin sensitivity and lipoprotein levels as well as reduced inflammation." (PMID 28632785, 2017). "Loss of first-phase insulin secretion is an early sign of developing type 2 diabetes (T2D)." (PMID 28481223, 2017). "Our study documented that reduced insulin sensitivity as assessed by the ISIMatsuda was significantly associated with an increase in the QTc interval, which represented the ventricular myocardial membrane electrical stabilization, in type 2 diabetes patients." (PMID 28912840, 2017). "It has been observed that decreased insulin sensitivity, decreased glucose tolerance, and increased blood glucose are strongly associated with the two- three fold higher level of inflammatory biomarkers in patients with obesity and type 2 diabetes." (PMID 28288617, 2017). "Moreover, melatonin treatment inhibits insulin secretion, which increases the risk of higher glucose levels, as increased melatonin signaling was proposed as a risk factor for Type 2 diabetes." (PMID 28884000, 2017). "Type 2 diabetes is a complex metabolic disorder that results from chronic inflammation-associated alterations in lipid metabolism and corresponding insensitivity of tissues to the actions of insulin." (PMID 28093504, 2017). "Moreover, recent intervention and epidemiological studies of berries in humans show that the ingestion of anthocyanins improves insulin sensitivity and decreases the risk of type 2 diabetes." (PMID 28748082, 2017). "Such information is needed to determine if saliva could be a non-invasive means to accurately measure postprandial insulin and potentially identify individuals at risk for type 2 diabetes due to hyperinsulinemia." (PMID 29099048, 2017). "The participants in the current study were healthy and absent of any chronic diseases, thus the effect of osteocalcin in modulating insulin secretion may be confined to individuals at risk of developing type-2 diabetes." (PMID 28286536, 2017). "Interestingly, several polymorphisms in the MTNR1B gene are associated with type 2 diabetes, fasting glucose concentration, and insulin secretion." (PMID 28396702, 2017). "The underlying mechanism of how PON1 Q192R polymorphism and statins interact on insulin secretion in patients with type 2 diabetes remains unclear." (PMID 29233102, 2017). "Strategies targeting to improve insulin sensitivity may provide therapeutic methods to ameliorate the prolongation of the QTc interval and its associated prognosis in type 2 diabetes patients." (PMID 28912840, 2017). "Type 2 diabetes results from a combination of insulin resistance in target organs and defective β-cells, while type 1 diabetes is due to the autoimmune-mediated loss of the pancreatic insulin-secreting β-cells, leading to insufficient glucose disposal." (PMID 28634486, 2017). "Impairment of β-cell glucose-stimulated insulin secretion (GSIS) is a hallmark of type 2 diabetes." (PMID 28428639, 2017).
type 2 diabetes (continued). "Although results from ZnT8 null mice suggest that increasing ZnT8 could improve insulin secretion and glycemic control, loss of function mutations in ZnT8 suggest a protective role for this transporter in type 2 diabetes." (PMID 29157234, 2017). "Therefore, based on the findings presented here, it is proposed that the discrimination of type 1 diabetes and type 2 diabetes should be based on the presence of insulin-deficient islets." (PMID 27796420, 2017). "Type 2 diabetes is caused by defects in both insulin sensitivity and insulin secretion." (PMID 28544529, 2017). "Our observation linking evening higher-GI-CHO to insulin sensitivity is in line with our hypothesis that evening rather than morning intake of higher-GI foods is potentially detrimental for risk factors of type 2 diabetes." (PMID 28604592, 2017). "In summary, our data suggest that patients with type 2 diabetes treated with insulin may be at a lower risk for the loss of skeletal muscle mass in the lower extremities, compared with those who do not receive insulin treatment." (PMID 28246927, 2017). "Multiple mechanisms underlie defective insulin secretion and responses in type 2 diabetes." (PMID 26904288, 2016). "Therefore, the serum amylase levels were positively associated with insulin secretion and insulin sensitivity in both asymptomatic subjects and type 2 diabetic patients." (PMID 27606813, 2016). "These responses drive cytosolic Ca2+ ([Ca2+]i) oscillations which, in turn, induce pulsatile insulin release, and defects in their generation may be associated with the loss of glucose homeostasis in type 2 diabetes." (PMID 26918892, 2016). "Further, we showed that bromocriptine, a known dopamine D2/D3 receptor agonist and newly approved drug used for treatment of type II diabetes mellitus, also decreased glucose-stimulated insulin secretion in islets to levels comparable to those caused by dopamine treatment." (PMID 26849707, 2016). "The results of this study demonstrate that plant fractions and isolates improve the main physiological and morphological changes caused by type II diabetes and decrease food and water intake, total cholesterol, triglycerides, and glucose, thus normalizing body weight and blood insulin levels." (PMID 27843476, 2016). "Type 2 diabetes is caused by cells insensitivity to insulin and insufficient production of insulin." (PMID 26810997, 2016). "Leptin and insulin are present in the hypothalamic neurons that are involved in body weight regulation, and the loss of leptin and insulin in the hypothalamus can promote obesity and type 2 diabetes." (PMID 27375435, 2016). "The elderly obese patients with long-standing and poorly controlled type 2 diabetes treated with high doses of insulin are at high risk of cancer development and they should be rigorously assessed towards malignancies, particularly breast cancer in women and colorectal cancer in men." (PMID 27724912, 2016). "The pathophysiological mechanisms of type 2 diabetes were a deficiency in both islet β cell secretion and impaired insulin action, which in turn may be responsible for decreasing basal serum amylase secretion." (PMID 27606813, 2016). "In the initial stages of type 2 diabetes associated with the hyperfunction of insulin‐producing β‐cells, increased levels of insulin could down‐regulate the nCEH expression in macrophages, thereby contributing to atherogenesis." (PMID 26493158, 2016). "In this analysis of 12,525 middle-aged and elderly Brazilians, we found sex-specific associations with low birth weight and prevalence of adult-onset diabetes and adult measures of glucose homeostasis (fasting and post-load hyperglycemia, insulin resistance, and β cell dysfunction)." (PMID 27845438, 2016). "Either defects in insulin secretion, type 1 diabetes, or in the action of insulin, type 2 diabetes, may cause the hyperglycemia which over time results in damage and dysfunction to many organs." (PMID 27300722, 2016).